CCND1 (cyclin D1)
Diseases named in the same sentence as CCND1 in open-access papers (continued):
Sharing a sentence is not in itself a finding about the gene and the disease.
tumor (continued). "Among the cyclin D1-negative tumours, 21 (78%) were positive for p16, a currently accepted surrogate marker for the presence of HPV DNA." (PMID 23672832, 2013). "However, these cells grew into much smaller tumors than the cells expressing SCR, which strongly suggests that Cyclin D1, like VEGF, also promoted tumor growth by the VHL-/- cancer cells in mice." (PMID 24260413, 2013). "Some of the miRNAs with recently identified targets in vitro in various tumor settings other than GIST include: miR-132 targeting Rb1, miR-193b targeting CCND1 and Mcl-1, miR-455-3p targeting Smad2, miR-125b targeting Mcl-1 and Bcl-2 and miR-542-5p targeting survivin." (PMID 23717541, 2013). "A high hip circumference was associated with beta-catenin negative (ptrend =0.036), cyclin D1 positive (ptrend =0.034), p 53 positive (ptrend =0.009) and MSS (ptrend =0.038) tumours." (PMID 24256736, 2013). "Moreover, daily treatment of metformin led to a substantial inhibition of tumor growth in a xenograft model with concomitant decrease in the expression of proliferating cell nuclear antigen (PCNA), cyclin D1 and p-mTOR." (PMID 24351837, 2013). "Further, cyclin D1 has been described to express itself mainly in the peripheral layers of tumour islands and not in the cells exhibiting mitosis." (PMID 22629227, 2012). "Strong evidence exists supporting a tumor suppressor function for miR-33a via repression of proto-oncogene Pim-1 and inhibition of expression of cyclin-dependent kinase 6 (CDK6) and cyclin D1 (CCDN1), both of which results in reduced cellular proliferation and cell-cycle progression." (PMID 22857597, 2012). "In particular, downregulation of TGFβ receptors, Smad7, MMPs, cyclin D1, and NF-κB by chlorophyllin and ellagic acid may play a key role in impeding the development of HBP tumours." (PMID 22485181, 2012). "In addition, UA significantly down-regulated the expression levels of cyclin D1 and COX-2 but up-regulated the levels of caspase-3 as revealed by immunohistochemical analysis of tumor tissue sections." (PMID 22427843, 2012). "Two tumor-promoting proteins regulated by EIF-4E—VEGF and cyclin D1—were also reduced." (PMID 22989709, 2012). "Western blot analysis on the dissected tumor tissues collected on Day 36 showed that both PITX2 stable expressing clones (C4 and C5) of SKOV3 expressed high levels of PITX2 and concomitant with elevated expressions of Cyclin-D1 and C-myc." (PMID 22615897, 2012). "Thus, we collected tissue pairs of adjacent normal and tumor tissues that overexpressed PLSCR1 and examined the expression of the adaptor protein Shc, Src, and cyclin D1." (PMID 23259795, 2012). "Together, these data strongly suggest that LPP3 is not a tumor promoting factor, but it amplifies β-catenin signaling and CYCLIN-D1 activity to potentiate SW480 growth." (PMID 21569306, 2011). "Given the high predictive accuracy and quantitative nature of the CCND1/CDKN2A expression assay, the assay could be utilized to stratify patients for anti-tumor agents with preferential effects on either RB1-positive or -negative tumors." (PMID 21447152, 2011). "Next, to examine whether CCND1 and CDKN2A could be utilized as an RB1 classifier in vivo, the RB1 status was determined in xenograft tumor samples." (PMID 21447152, 2011). "The tumor cells expressed CD56 and Cyclin D1 protein in 6 cases each (18.8%)." (PMID 22182738, 2011). "Our data showed that although expression of cdk-4, cdk-6, and p27 was not affected by sorafenib, the levels of cyclin D1, cyclin cdk-2, and cyclin B1 in sorafenib-treated tumours were significantly reduced as compared with controls (P<0.05)." (PMID 21407223, 2011).
tumor (continued). "Furthermore, co-transfection of BRG1 siRNA and p-Akt1 restored cell growth accompanied by upregulation of p-Akt, p-GSK-3β and cyclin D1 levels, whereas transduction of PTEN siRNA decreased tumour-suppressing effect of BRG1 silencing." (PMID 21102582, 2011). "CCND1 protein expression was assessed in 224 cases by IHC; seven cases were excluded from final evaluation due to the lack of tumor cells in the tissue sections." (PMID 22065993, 2011). "Similarly, WWP1, SDC1 (syndecan 1), EZH2, CCND1, ADAM9 and MEMO1 have oncogenic activities and are targeted by the potentially tumor suppressor miRNA miR-195, miR-10b, let-7c, miR-17 and miR-125b." (PMID 21375733, 2011). "Finally, CDDO up-regulates p21 and down-regulates cyclin D1 and Bcl-2, thus inducing cell-cycle arrest and apoptosis in MDA-MB-435 tumor cells." (PMID 21524306, 2011). "We found significant correlation of EGFR expression and tumor stage (P = 0.042), β-catenin and tumor size (P = 0.025) and stage (P = 0.031), and of EGFR expression and β-catenin cytoplasmic/nuclear expression and cyclin-D1 immunoactivity (P < 0.0001 for both)." (PMID 20302655, 2010). "In mammary gland tissue samples of tumor-bearing mice, most epithelial cells were negative for cyclin D1 staining and several "hot spots areas" (areas with high expression of cyclin D1) were observed." (PMID 20092659, 2010). "Indeed, the expression of two well-known AP-1 regulated genes, cyclin D1 and uPA, was suppressed by TSA suggesting the strong anti-tumor activities of TSA." (PMID 20609221, 2010). "Another cyclin D1 function that can lead to tumour formation is the transcriptional control that does not involve CDKs." (PMID 21176227, 2010). "In tumor cells, there was elevated EGFR immunoreactivity in most samples, decreased membranous staining and increased cytoplasmic/nuclear staining of β-catenin, and positive staining for cyclin D1." (PMID 20302655, 2010). "No significant changes in expression of cyclin D1 or Ki67 with sorafenib treatment were demonstrable in the 15 patients with pre-and post-treatment tumor samples." (PMID 21206909, 2010). "Notably, in some serial sections of tumor cells, there was high EGFR immunoreactivity that was accompanied by cytoplasmic and nuclear β-catenin staining and high cyclin D1 immunostaining." (PMID 20302655, 2010). "Tumor cells have increased levels of OPN, c-jun, cyclin D1 and uPA." (PMID 20609221, 2010). "The molecular analysis of tumor samples and in vitro experiments indicated that MTA induces cytostatic rather than pro-apoptotic effects inhibiting the phosphorylation of Akt and S6 ribosomal protein and inducing the down-regulation of cyclin D1." (PMID 20529342, 2010). "CCND1 was also overexpressed in 1 out of 27 (4%) tumours with cytoplasmic or negative CTNNB1 staining." (PMID 19293793, 2009). "Correlation of CCND1 overexpression and CTNNB1 nuclear localisation was not absolute in either cohort, with some tumours displaying only cytoplasmic or negative CTNNB1 staining overexpressing CCND1." (PMID 19293793, 2009). "A total of 4 out of 17 (24%) tumour samples displaying cytoplasmic or negative CTNNB1 staining also overexpressed CCND1." (PMID 19293793, 2009). "The ability of the anti-Wnt-1 antibody to down-regulate the expression of downstream targets of Wnt/β-catenin signaling, including c-Myc, cyclin D1, and survivin, suggest that a broad spectrum of cellular mechanisms can be triggered in concert to halt HCC tumor growth." (PMID 19778454, 2009). "In this study, expression of cyclin D1 and c-myc was markedly increased in HCC tissues, compared with normal liver tissues but the expression levels of these two genes were higher in peritumor cells than that of tumor cells." (PMID 19402906, 2009).
tumor (continued). "They demonstrate that, in EOC, GILZ increases tumor cell proliferation, activates AKT, down-regulates p21 and promotes cyclin D1 expression; all these molecules are involved in the progression of malignant tumors and their deregulations are often associated to poor clinical outcome." (PMID 19814803, 2009). "As a model system, we examined CCND1 and HER-2/neu oncogenes in normal mucus and tumoral tissue of both the esophagus and stomach by using a FISH assay, since these genes have been shown to become amplified and/or over-expressed in these two types of tumor." (PMID 21637674, 2009). "In contrast no upregulation of CCND1 gene expression was detected in the premalignant lesions adjacent to non-amplified tumours." (PMID 19287496, 2009). "Considering the different functions of cortactin, cyclin D1 and FADD it would be interesting to see whether these genes, coamplified in the same tumour, have a function at specific stages of tumorigenesis." (PMID 18268491, 2008). "Full sections of representative tumors exhibiting CCND1 amplification and low expression of Chk1 were stained using CISH to verify that tumor cells with low Chk1 expression actually were amplified in the CCND1 gene (data not shown)." (PMID 18823530, 2008). "Cyclin D1 was expressed almost uniformly in DCIS usually with high proportion of positive tumor cells and did not correlate with prognosis in our study." (PMID 21892261, 2008). "We show that whereas cyclin D1 expression is low or absent in non-neoplastic tissue, its levels are increased in the majority of localised tumours." (PMID 17375037, 2007). "First, the majority of tumours scored high for cytoplasmic cyclin D1 with little or no nuclear cyclin D1 reactivity (25/36)." (PMID 17375037, 2007). "This study examined only three prostate-derived metastatic tumours, all of which showed low nuclear cyclin D1 staining and lacked cytoplasmic staining." (PMID 17375037, 2007). "Of the combined 102 tumour specimens, the largest fraction scored negative for cyclin D1 (40 and 62.2%; TA1 and TA2, respectively) suggesting that cyclin D1 expression is not requisite for tumour maintenance." (PMID 17375037, 2007). "This poor prognosis in tumors over-expressing cyclin D1 was found to be independent of other clinicopathological parameters such as tumor stage, nodal or distant metastasis, or degree of differentiation." (PMID 16953893, 2006). "Cyclin D1 over-expression was limited to tumor cells and no immunostaining was noted on the surrounding normal epithelium of the nasopharynx." (PMID 16953893, 2006). "This unexpected phenomenon was first observed in NIH3T3 cells, wherein cyclin D1b but not cyclin D1 was sufficient to drive cellular transformation in vitro (as monitored by focus formation assays) or tumor formation in vivo." (PMID 16863592, 2006). "We have also reported lack of correlation between cyclin D1 and pRb positivity and clinico-pathological tumor characteristics." (PMID 16426443, 2006). "Our results demonstrate that cyclin D1, cyclin A, histone H3 and Ki-67 are overexpressed in a subset of CRC, however only cyclin D1 and cyclin A overexpression correlates with poor differentiation and tumor progression." (PMID 15385053, 2004). "The relapse-free survival time of patients with CCND1-amplified tumours was shorter than that of patients without CCND1 alterations, while that of patients with CCND1-unamplified-overexpressed tumours was longer (P=0.011)." (PMID 11870541, 2002). "Only one (3.1%) of the 32 patients with CCND1-unamplified-overexpressed tumours was oestrogen receptor-negative, compared with 41 (40.2%) of the other 102 patients." (PMID 11870541, 2002).
tumor (continued). "Interestingly, the CCND1-amplified-overexpressed tumours contained larger amounts of CCND1 mRNA (12 tumours; mean NCCND1 17.9, range 7.6 to 43.7) than did the CCND1-unamplified-overexpressed tumours (32 tumours; mean NCCND1 5.6; range 3.3 to 8.6)." (PMID 11870541, 2002). "In addition, PMV/Ivm-NC secured pronounced tumor-growth inhibition, down-regulation of oncogenic markers (VEGF and cyclin D1), upregulation of pro-apoptotic Bax and caspase-3, and enhanced immune-infiltration of CD4+ and CD8+ T-cells, suggesting Ivm-induced immunogenic cell death." (PMID 41495333, 2026). "NO influences tumor cell proliferation through a bidirectional regulatory mechanism: at low concentrations (≤100 nM), NO activates the PI3 K/Akt and AMPK signaling pathways, enhances cyclin D1 expression, accelerates the G1/S phase transition, and thereby promotes tumor cell proliferation." (PMID 41036604, 2025). "Contrary to some previous studies, our results showed weaker expression of cyclin D1 in well-differentiated OSCC and markedly higher expression in poorly differentiated cases, suggesting that cyclin D1 expression increases with decreasing tumor differentiation." (PMID 41541922, 2025). "However, there are certain requirements for inclusion in clinical patients, for example, tumor tissue samples should have increased protein expression of KLF5, XPO1 and Cyclin D1, and no mutation of RB1 and positive expression in the cytoplasm." (PMID 39888288, 2025). "In addition, another investigation has demonstrated the m6A-dependent role of YTHDF1 in regulating the translation efficiency of cyclin-dependent kinase 2 (CDK2), CDK4, and cyclin D1 (CCND1), thereby exerting control of NSCLC cell proliferation and xenograft tumor formation." (PMID 39342406, 2024). "Tumor cells were negative for Cyclin D1, and P16 was non-contributory." (PMID 39469368, 2024). "For example, the regulation of CENPA could affect CCND1 and CDK4/6, interfering with cell cycle, and also affect the activity of the Wnt signalling pathway, ultimately affecting the proliferation and growth of tumour cells." (PMID 39620895, 2024). "Conversely, many genes have broad, often bi-/multimodal distribution (for example CD44, CCND1 and CD74 in tumour and STAT1 in both compartments for all p16/HPV subgroups), potentially reflecting spatial context – tumour core versus tumour periphery or tumour-adjacent versus more distant stroma." (PMID 39328208, 2024). "There was a significant reduction in the expression of the proliferation marker Ki67 in the drug-treated mice, and decreased expression of several cell cycle markers including CCND1, and E2F1, which could account for the reduction in tumor weight in response to Bay." (PMID 38994944, 2024). "The amplification of CCDN1, leading to cyclin D1 over-expression, is common in OSCC (15–55% of tumours), correlates with oral epithelial tumour progression and is associated with both the non-diploid status of tumours and with CIN." (PMID 36671795, 2023). "Moreover, immunohistochemical staining showed that tumor with Ki67 exon 7 knockdown showed reduced expression of PCNA (cell proliferation marker), Cyclin D1 (cell cycle marker), and N-cadherin (epithelial to mesenchymal transition, EMT, marker), but increased expression of E-cadherin (EMT marker)." (PMID 36835286, 2023). "Cyclin D1 might also play a role in GC formation and multinucleation, as opposed to purely cell proliferation in this tumour, as it has mostly been detected in smaller GCs with less nuclei." (PMID 37509363, 2023). "Moreover, because cyclin D1 expression was impaired in shIRAK2 BCSC1 xenografts, it may be responsible for delayed tumour growth." (PMID 36768848, 2023).
tumor (continued). "Furthermore, TAMs promote tumor progression and invasion by secreting matrix metalloproteinases (MMPs), and of these, MMP1 can activate cdc25a/CDK4-cyclin D1 and p21/cdc2-cyclin B1 complexes to accelerate the growth of colon cancer cells via the regulation of MYC expression." (PMID 36966168, 2023). "Researchers found that Nav1.5 knockdown could inhibit the expression of β-catenin, cyclin D1, and MYC in the WNT/β-catenin signaling pathway, thus promoting the apoptosis of tumor cells and effectively inhibiting the migration and invasiveness of tumor cells." (PMID 36966168, 2023). "Cyclin D1's high expression was correlated with tumor size (P = 0.02), but not with age, gender, ethnicity, tumor location, differentiation, lymph node metastasis, invasion depth, AJCC stage, vascular invasion, nerve invasion, and blood-derived metastasis (P > 0.05)." (PMID 35242498, 2022). "Most cases of positive cyclin D1 showed absence of tumor necrosis (P= 0.073)." (PMID 35942997, 2022). "To address whether our whole transcriptome analysis results are in agreement with the previously published literature, we evaluated the expression levels of CCND1 and SOX11 mRNAs as well as ROR1-AS1 and LINK-A (LINC001139) lncRNA expression levels in MCL tumor tissue samples." (PMID 36359790, 2022). "Additionally, Rotterlin, a protein kinase inhibitor that exerts its anti-tumor activity in various types of human cancers, was found to upregulate DDX3X expression in HCC that subsequently downregulates cyclin D1 expression and increases p21 level, leading to cell cycle arrest." (PMID 35954483, 2022). "In addition, HPV-negative tumors often show amplification of 11q13 including CCND1 and focal deletions of tumor suppressor genes including CDKN2A." (PMID 35884529, 2022). "In these S6K1-overexpressed tumours, palbociclib monotherapy could not successfully downregulate the levels of cell cycle-related genes, such as p-Rb (P = 0.962) and cyclin D1 (P = 0.320)." (PMID 36042494, 2022). "The tumor mass in the xenograft models will be examined for apoptosis alternation such as caspase enzyme activity or DNA repair enzymes (such as Uracil-DNA glycosylase) and tested for the interaction of HPV oncoprotein and EGFR nuclear trafficking-related factors such as cyclin D1." (PMID 36358752, 2022). "This interaction activates target genes like c-myc, cyclin d1, matrix metalloproteinase and vascular endothelial growth factor (VEGF) that are involved in various processes of tumorigenesis, including tumor initiation, tumor growth, cell senescence, cell death, differentiation and metastasis." (PMID 35178201, 2022). "However, PTL was a potent drug to induce the S-phase arrest in nonpromoted cells and block tumor-promoted cells at S to G2/M phases as well as to modulate the p65 binding and chromatin structure on p21 and cyclin D1 promoters regulating their gene expression." (PMID 34835969, 2021). "Similarly, YTHDF1 deficiency could inhibit NSCLC cell proliferation and xenograft tumor formation by regulating the translational efficiency of cell-cycle-related genes, such as CDK2, CDK4, and cyclin D1." (PMID 34359836, 2021). "Thus, according to our data, CCND1 could be a target gene of ELF5, indicating that the execution of a tumor suppressor via CCND1 may be another action mechanism of ELF5." (PMID 33742100, 2021). "In agreement with this, we found that besides cancer stemness genes, the key oncogenes associated with cell proliferation, such as CCND1, can also be significantly suppressed by JQ1, which supports the phenomena that JQ1 targets both quiescent CSCs and fast proliferating non-stem tumor cells." (PMID 34172737, 2021).